ARSI (arylsulfatase family member I)
Description:
Displays arylsulfatase activity at neutral pH, when co-expressed with SUMF1; arylsulfatase activity is measured in the secretion medium of retinal cell line, but no activity is recorded when measured in cell extracts. Lacks arylsulfatase activity.
Synonyms: ASI; FLJ16069; SPG66
Tractability: Antibody: UniProt places it where antibodies can reach, with high confidence; UniProt predicts a signal peptide or a membrane-spanning region; its Gene Ontology location is reachable by antibodies, with medium confidence.
Gene: Protein-coding gene on chromosome 5 (150,296,343 to 150,339,307, reverse strand). Ensembl gene ENSG00000183876.
Subcellular location: Secreted; Endoplasmic reticulum
Subcellular location (Human Protein Atlas): Golgi apparatus; Vesicles; Predicted to be secreted
Pathways (Reactome):
Metabolism: Glycosphingolipid catabolism
Metabolism of proteins: The activation of arylsulfatases
Gene Ontology:
Molecular function: protein binding; arylsulfatase activity; sulfuric ester hydrolase activity
Cellular component: endoplasmic reticulum; extracellular region; endoplasmic reticulum lumen
Genetic constraint (gnomAD): Loss-of-function variants: 19 observed, 19.86 expected, observed/expected ratio (o/e) 0.96, 90% interval 0.67 to 1.4. The upper end of that interval is the gene's LOEUF score, 1.4, which puts it in group 5 of 6, group 1 being the genes least tolerant of losing a copy. Missense variants: 377 observed, 427.41 expected, observed/expected ratio (o/e) 0.88, 90% interval 0.81 to 0.96. Synonymous variants: 166 observed, 175.79 expected, observed/expected ratio (o/e) 0.94, 90% interval 0.83 to 1.07.
Homologues: Orthologues: chimpanzee ARSI (99% identical), macaque ARSI (99% identical), dog ARSI (96% identical), rabbit ARSI (96% identical), guinea pig ARSI (96% identical), mouse Arsi (96% identical), pig ARSI (92% identical), rat Arsi (89% identical), tropical clawed frog arsi (79% identical), zebrafish arsia (66% identical), Drosophila melanogaster CG7402 (28% identical), Drosophila melanogaster CG32191 (26% identical), and 6 more. Paralogues in human: ARSJ (60% identical), ARSB (48% identical), ARSL (27% identical), ARSD (25% identical), STS (25% identical), ARSA (24% identical), ARSH (24% identical), GALNS (24% identical), ARSF (24% identical), ARSG (22% identical), SULF2 (20% identical), SULF1 (20% identical), and 4 more.
Diseases named in the same sentence as ARSI in open-access papers:
ARSI is named in the same sentence as 13 diseases in open-access papers, as found by Europe PMC text mining. Sharing a sentence is not in itself a finding about the gene and the disease. The quoted sentences say what the papers report.
head and neck squamous cell carcinoma (1 paper, 2022). A squamous cell carcinoma that arises from any of the following anatomic sites: lip and oral cavity, nasal cavity, paranasal sinuses, pharynx, larynx, and salivary glands. "However, the expressions and prognostic value of Arylsulfatase I (ARSI), a sulfatase gene family member, in head and neck squamous cell carcinoma (HNSC) have not been fully established." (PMID 35870182, 2022).
lung carcinoma (1 paper, 2022). "ARSI was found to be principally expressed in embryonic tissues and in the A549 cell line, which originates from lung carcinoma." (PMID 35870182, 2022).
lymph node metastasis (1 paper, 2025). "The associations between ARSI expression and clinicopathological features, such as tumor size, lymph node metastasis, and advanced TNM stage, underscore its relevance to PTC aggressiveness and disease progression." (PMID 39744439, 2025).
lysosomal storage disease (1 paper, 2009). A metabolic disorder caused by mutations in proteins critical for lysosomal function, including lysosomal enzymes, lysosomal integral membrane proteins, and proteins involved in the post-translational modification and trafficking of lysosomal proteins. "As the mutation of ARSs has been known to cause lysosomal storage diseases accompanying RP-like symptoms, we thought that ARSI preferentially expressed in RPE could be a candidate gene responsible for RP." (PMID 19262745, 2009). "Although ARSI may not be a causative gene for lysosomal storage diseases, preferentially expressed in the eye, ARSI would be a candidate gene causing inherited eye diseases for future mutation screening." (PMID 19262745, 2009).
retinitis pigmentosa (1 paper, 2009). Retinitis pigmentosa (RP) is an inherited retinal dystrophy leading to progressive loss of the photoreceptors and retinal pigment epithelium and resulting in blindness usually after several decades. "The aim of this study was to characterize the arylsulfatase I (ARSI) gene that has been shown to be preferentially expressed in the human retinal pigment epithelium cell line ARPE-19 and to propose it as a candidate gene responsible for inherited eye diseases such as retinitis pigmentosa (RP)." (PMID 19262745, 2009).
cancer (3 papers, 2021 to 2025). A tumor composed of atypical neoplastic, often pleomorphic cells that invade other tissues. "Pan‐cancer analysis showed that ARSI mRNA expressions were associated with almost all immunosuppressive‐associated genes in most cancers, apart from DLBC and SKCM." (PMID 35870182, 2022). "Kaplan–Meier survival analysis was used to study the association between ARSI expressions and prognostic outcomes in various cancers." (PMID 35870182, 2022). "In this study, ARSI expressions were associated with tumor‐infiltrating immune cells, which could influence tumor behaviors in multiple cancer types." (PMID 35870182, 2022). "Our findings of EREG involvement in ARSI-driven ferroptosis resistance extend previous research that has highlighted EREG's role in other cancer types." (PMID 39744439, 2025). "Studies evaluating ARSI expression across various human tissues and cancer cell lines have revealed its predominant presence in tissue remodeling during both tumor progression and embryonic development." (PMID 39744439, 2025). "Then, univariate Cox regression, Kaplan–Meier, and the Pearson's correlation analyses were performed to determine correlations between ARSI expressions and cancer prognosis, immune cell status, and drug sensitivity." (PMID 35870182, 2022). "Methylation levels of the ARSI promoter were negatively correlated with ARSI expressions in 23 cancer types and were most pronounced in SKCM." (PMID 35870182, 2022). "TCGA; The Cancer Genome Atlas, GTEx; Genotype‐Tissue Expression, GSVA; Gene Set Variation Analysis, GSEA, Gene Set Enrichment Analysis, ARSI; Arylsulfatase I, MSI; Microsatellite instability, TMB; Tumor mutational burden." (PMID 35870182, 2022). "Arylsulfatase I (ARSI) is one of the seventeen members of sulfatase gene family, whose aberrant expressions contribute to cancer cell migration." (PMID 35870182, 2022). "Expressions of ARSI have been evaluated in different human tissues and cancer cell lines." (PMID 35870182, 2022). "In conclusion, ARSI is a promising prognostic biomarker in pan‐cancer, especially HNSC." (PMID 35870182, 2022). "Analysis of data from the ImmuCellAI database revealed that ARSI was positively correlated with infiltration levels of macrophages, DC, iTerg, monocytes, and NKT cells, but negatively correlated with neutrophils, B cells, Tgd, Tem, and Th17 cells in TCGA pan‐cancer." (PMID 35870182, 2022). "However, ARSI and PHYH have not been previously studied in cancers." (PMID 33277966, 2021).
tumor (2 papers, 2022 to 2025). "GSEA also showed that tumor progression-related signaling pathways, including the ECM_receptor_interaction and JAK_STAT_signaling pathways, were closely associated with ARSI expression in PTC." (PMID 39744439, 2025). "It was established that ARSI was significantly associated with pathways that mediate tumor cell invasion, migration, and metastasis in HNSC." (PMID 35870182, 2022). "Expressions of ARSI negatively correlated with tumor mutation burden or microsatellite instability and positively correlated with immune‐related genes." (PMID 35870182, 2022). "Besides, comprehensive analyses of the ARSI gene at tumor mutation burden (TMB) and microsatellite instability (MSI) levels were performed." (PMID 35870182, 2022). "Consistently, EGER overexpression also mitigated the decrease in the number of dead cells and the invasion of tumor cells in the ARSI-knockdown group." (PMID 39744439, 2025). "Functional studies revealed that ARSI promoted the tumor growth, cell migration, and epithelial-mesenchymal transition (EMT) of BRAFV600E PTC cells in vitro." (PMID 39744439, 2025). "In vivo studies confirmed that ARSI suppression inhibited tumor growth and metastasis in mouse models of PTC." (PMID 39744439, 2025). "In this study, we found that ARSI levels were highly elevated in tumor tissues, especially HNSC, compared with normal or adjacent non‐tumor tissues." (PMID 35870182, 2022). "cBioPortal, which has more than 28,000 tumor samples, was used to investigate genetic alterations of ARSI." (PMID 35870182, 2022). "ARSI may modulate extracellular matrix remodeling, cell signaling pathways, and immune responses in the tumor microenvironment, thereby influencing tumor growth and metastasis." (PMID 39744439, 2025). "ARSI is involved in tissue remodeling during tumor growth, as well as during embryonic development." (PMID 35870182, 2022). "In addition, GSVA and GSEA showed that ARSI was highly involved in tumor cell escape and inflammatory responses." (PMID 35870182, 2022). "Data suggest that ARSI may be involved in tumor immune evasion, leading to poor prognosis of HNSC." (PMID 35870182, 2022). "In addition, we found that ARSI expressions were associated with immune cell infiltrations and tumor metastasis, but not their causality." (PMID 35870182, 2022).
ARSI also shares sentences with these, for which no sentence is quoted: colon tumor (1 paper); coronary artery disease (1); embryonic carcinoma (1); glioma (1); Pan (1); papillary thyroid carcinoma (1).